RN7SL473P (RNA, 7SL, cytoplasmic 473, pseudogene)
Gene: Miscellaneous RNA gene on chromosome 1 (150,566,562 to 150,566,860, reverse strand). Ensembl gene ENSG00000277452.
Homologues: Orthologues: macaque Metazoa_SRP (93% identical). Paralogues in human: RN7SL600P (93% identical), RN7SL1 (84% identical), RN7SL3 (84% identical), RN7SL2 (83% identical), RN7SL45P (81% identical), RN7SL679P (81% identical), RN7SL664P (80% identical), RN7SL322P (79% identical), RN7SL444P (79% identical), RN7SL481P (79% identical), RN7SL828P (79% identical), RN7SL126P (79% identical), and 701 more.